H3-3B (H3.3 histone B)
Description:
Variant histone H3 which replaces conventional H3 in a wide range of nucleosomes in active genes. Constitutes the predominant form of histone H3 in non-dividing cells and is incorporated into chromatin independently of DNA synthesis. Deposited at sites of nucleosomal displacement throughout transcribed genes, suggesting that it represents an epigenetic imprint of transcriptionally active chromatin. Nucleosomes wrap and compact DNA into chromatin, limiting DNA accessibility to the cellular machineries which require DNA as a template. Histones thereby play a central role in transcription regulation, DNA repair, DNA replication and chromosomal stability. DNA accessibility is regulated via a complex set of post-translational modifications of histones, also called histone code, and nucleosome remodeling.
Synonyms: H3.3B; H3F3B; BRYLIB2
Tractability: Small molecule: a structure with a bound ligand is known. Antibody: its Gene Ontology location is reachable by antibodies, with high confidence. PROTAC: UniProt records ubiquitination sites on it; ubiquitination databases record sites on it.
Gene: Protein-coding gene on chromosome 17 (75,776,434 to 75,785,893, reverse strand). Ensembl gene ENSG00000132475.
Subcellular location: Nucleus; Chromosome
Subcellular location (Human Protein Atlas): Nucleoplasm
Pathways (Reactome):
Gene expression (Transcription): B-WICH complex positively regulates rRNA expression; DNA methylation; ERCC6 (CSB) and EHMT2 (G9a) positively regulate rRNA expression; MLL4 and MLL3 complexes regulate expression of PPARG target genes in adipogenesis and hepatic steatosis; NoRC negatively regulates rRNA expression; PRC2 methylates histones and DNA; RNA Polymerase I Promoter Escape; RNA Polymerase I Promoter Opening; RUNX1 regulates genes involved in megakaryocyte differentiation and platelet function; RUNX1 regulates transcription of genes involved in differentiation of HSCs; Regulation of endogenous retroelements by KRAB-ZFP proteins; Regulation of endogenous retroelements by Piwi-interacting RNAs (piRNAs); Regulation of endogenous retroelements by the Human Silencing Hub (HUSH) complex; SIRT1 negatively regulates rRNA expression; Transcriptional regulation by small RNAs
Chromatin organization: CHD1 and CHD2 subfamily; CHD6, CHD7, CHD8, CHD9 subfamily; Interaction of NuRD complexes with transcription factors; NuRD complex assembly
Developmental Biology: Activation of anterior HOX genes in hindbrain development during early embryogenesis; Chromatin modifications during the maternal to zygotic transition (MZT); Replacement of protamines by nucleosomes in the male pronucleus; Transcriptional regulation of granulopoiesis
Signal Transduction: Activated PKN1 stimulates transcription of AR (androgen receptor) regulated genes KLK2 and KLK3; Estrogen-dependent gene expression; Formation of the beta-catenin:TCF transactivating complex; Pre-NOTCH Transcription and Translation
Cell Cycle: Condensation of Prophase Chromosomes; Inhibition of DNA recombination at telomere
Cellular responses to stimuli: Oxidative Stress Induced Senescence; Senescence-Associated Secretory Phenotype (SASP)
Immune System: FXIIa activates plasma kallikrein-kinin system; Regulation of PD-L1(CD274) transcription
Cell-Cell communication: Negative Regulation of CDH1 Gene Transcription
DNA Replication: Assembly of the ORC complex at the origin of replication
Disease: Defective pyroptosis
Hemostasis: Factors involved in megakaryocyte development and platelet production
Metabolism of proteins: Amyloid fiber formation
Reproduction: Meiotic recombination
Gene Ontology:
Molecular function: nucleosomal DNA binding; protein binding; RNA polymerase II cis-regulatory region sequence-specific DNA binding; RNA polymerase II core promoter sequence-specific DNA binding; structural constituent of chromatin; DNA binding; protein heterodimerization activity
Biological process: nucleosome assembly; positive regulation of cell growth; heterochromatin formation; kinetochore assembly; mitotic metaphase chromosome alignment; telomere organization
Cellular component: chromosome; chromosome, telomeric region; extracellular exosome; nucleoplasm; nucleosome; nucleus; protein-containing complex; extracellular region; kinetochore
Genetic constraint (gnomAD): Loss-of-function variants: 2 observed, 12.97 expected, observed/expected ratio (o/e) 0.15, 90% interval 0.062 to 0.49. The synonymous counts are far from expectation, so gnomAD's model fits this gene poorly and the ratio says little. Missense variants: 39 observed, 190.26 expected, observed/expected ratio (o/e) 0.2, 90% interval 0.16 to 0.27. Synonymous variants: 133 observed, 78.3 expected, observed/expected ratio (o/e) 1.7, 90% interval 1.47 to 1.92.
Homologues: Orthologues: chimpanzee H3-3A (100% identical), Caenorhabditis elegans his-71 (99% identical). Paralogues in human: H3-3A (100% identical), H3C13 (97% identical), H3C14 (97% identical), H3C15 (97% identical), H3C1 (96% identical), H3C10 (96% identical), H3C11 (96% identical), H3C12 (96% identical), H3C2 (96% identical), H3C3 (96% identical), H3C4 (96% identical), H3C6 (96% identical), and 8 more.
Diseases named in the same sentence as H3-3B in open-access papers:
H3-3B is named in the same sentence as 4 diseases in open-access papers, as found by Europe PMC text mining. Sharing a sentence is not in itself a finding about the gene and the disease.
H3-3B shares sentences with these, for which no sentence is quoted: chondrosarcoma (1 paper); glioma (1); infection (1); male infertility (1).